GCH1 (GTP cyclohydrolase 1)
Diseases named in the same sentence as GCH1 in open-access papers (continued):
Sharing a sentence is not in itself a finding about the gene and the disease.
lentivirus infection (1 paper, 2022). Virus diseases caused by the Lentivirus genus. "Together, these data showed that the lentivirus infections and overexpression of TH, AADC, and GCH1 did not raise any additional adverse effects or safety concerns." (PMID 36550118, 2022).
leukemia (1 paper, 2022). A malignant (clonal) hematologic disorder, involving hematopoietic stem cells and characterized by the presence of primitive or atypical myeloid or lymphoid cells in the bone marrow and the blood. "Two recent studies revealed that GCH1/BH4 metabolism possesses an antagonistic effect against ferroptosis as an endogenously antioxidant system in fibroblast cells, fibrosarcoma cells, leukemia cells, and pancreatic cancer cells." (PMID 35223839, 2022).
lymph node metastases (1 paper, 2024). "We found that high expression intensity of GCH1 significantly correlated with lymph node metastases, vessel invasion, and pStage." (PMID 39723384, 2024). "GCH1 expression significantly correlated with lymph node metastases (p < 0.001), vessel invasion (p < 0.001), and pStage (p < 0.001)." (PMID 39723384, 2024).
multiple myeloma (1 paper, 2025). "MG132, a well-known proteasome inhibitor, and Bortezomib, an FDA-approved proteasome inhibitor for the treatment of multiple myeloma, significantly increased GCH1 protein levels in both control and shunt ECs, indicating that GCH1 undergoes rapid and regulatable proteasomal degradation." (PMID 39941119, 2025).
Myocardial fibrosis (1 paper, 2017). "Cardiomyocyte-specific overexpression of GCH1 decreased myocardial fibrosis and p-p38 MAPK but not microRNA-21 levels after MI." (PMID 28596578, 2017).
myocardial infarction (1 paper, 2017). Gross necrosis of the myocardium, as a result of interruption of the blood supply to the area, as in coronary thrombosis. "GTP cyclohydrolase 1 (GCH1) and its product tetrahydrobiopterin play crucial roles in cardiovascular health and disease, yet the exact regulation and role of GCH1 in adverse cardiac remodeling after myocardial infarction are still enigmatic." (PMID 28596578, 2017).
orchitis (1 paper, 2020). Inflammation of one or both testes due to viral or bacterial infections. "Our results show that melatonin may inhibit iNOS activity through p38MAPK/GCH1 pathways, reducing NO production in LPS-induced sheep orchitis." (PMID 33327643, 2020).
orofacial cleft (1 paper, 2016). A disorder of facial skeleton that is characterized by cleft lip and/or cleft palate that result in feeding, speech and hearing problems caused by failures during development. "This study demonstrates that the risk of NSCL/P is associated with variants of the GCH1 gene related to BH4 metabolism and provides some evidence of the relationships between morphological/functional shifts in the central nervous system and orofacial clefts." (PMID 26215833, 2016).
osteosarcoma (1 paper, 2024). A usually aggressive malignant bone-forming mesenchymal neoplasm, predominantly affecting adolescents and young adults. "Collectively, these data indicate that the GCH1/BH4 anti-ferroptotic system seems not involved in the regulation of ferroptotic sensitivity/resistance of osteosarcoma cells." (PMID 38368399, 2024). "However, no activation of this antiferroptotic pathways was observed in OS-resistant cell lines, while upregulation of GCH1 was evidenced in the most sensitive cell line, thus confirming that this mechanism is not involved in the resistance of osteosarcoma to ferroptosis execution." (PMID 38368399, 2024).
pancreatitis (1 paper, 2008). Inflammation of the pancreas. "The present study is the first to evaluate the GCH1 "pain-protective haplotype" in visceral pain, but our findings do not rule out the possibility that GCHI-dependent pathways play an important role in visceral pain involving other organs, or in small subsets of pancreatitis-associated pain." (PMID 19014702, 2008).
peripheral arterial disease (1 paper, 2023). A disorder of the arteries supplying the upper and lower extremity and the visceral organs. "Sodium tanshinone IIA sulfonate treatment improved angiogenesis by regulating the miR-133a/GCH-1 signaling pathway in experimental peripheral arterial disease (PAD) in diabetes." (PMID 37687031, 2023).
peritonitis (1 paper, 2018). Inflammation of the peritoneum (tissue that lines the abdominal wall and covers most of the organs in the abdomen). "We confirmed Gch1 deletion rendered inflammatory cells BH4 deficient in vivo, by inducing sterile peritonitis in mice using zymosan, to induce iNOS in recruited peritoneal exudate cells." (PMID 30573728, 2018).
preeclampsia (1 paper, 2021). Preeclampsia is a hypertensive disorder of pregnancy that is characterized by new-onset hypertension with proteinuria presenting after 20 weeks of gestation, and depending on mild or severe forms may initially present with severe headache, visual disturbances, and hyperreflexia. "Targeting endothelial cell Gch1 and BH4 biosynthesis may provide a novel therapeutic target for the prevention and treatment of pregnancy-related hypertension, preeclampsia, and fetal growth retardation." (PMID 34689592, 2021). "Thus, targeting endothelial cell GCH1 and BH4 biosynthesis may provide a novel therapeutic target for the prevention and treatment of pregnancy-related hypertension such as preeclampsia." (PMID 34689592, 2021).
pulmonary fibrosis (1 paper, 2024). Chronic progressive interstitial lung disorder characterized by the replacement of the lung tissue by connective tissue, leading to progressive dyspnea, respiratory failure, or right heart failure. "Taken together, these results indicate that GCH1 plays an important role in radiation-induced lung fibrosis." (PMID 38689083, 2024). "Since GCH1-mediated anabolism has been shown to regulate the fibrotic phenotype in vitro, we examined whether GCH1 affected radiation-induced pulmonary fibrosis in vivo." (PMID 38689083, 2024).
septic shock (1 paper, 2016). Shock caused by infection; frequently caused by gram negative bacteria, although some cases have been caused by other bacteria, viruses, fungi, and protozoa; characterized by fever, chills, tachycardia, tachypnea, and hypotension. "Thus, targeting endothelial cell Gch1 and BH4 biosynthesis may provide a novel therapeutic target for the treatment of circulatory collapse in patients with septic shock." (PMID 26276526, 2016).
spina bifida (1 paper, 2016). A congenital neural tube defect in which vertebrae are not fully formed. "In contrast to these expectations, in our study, the allele and genotype distributions of the three polymorphic variants of GCH1 regarded as linked with spina bifida risk (rs8007267, rs3783641, rs10483639) were found to be similar among NSCL/P affected children and controls." (PMID 26215833, 2016).
tuberculosis (1 paper, 2025). A chronic, recurrent infection caused by the bacterium Mycobacterium tuberculosis. "Collectively, these multi-tiered validation data robustly support the involvement of ASPHD2, GCH1, and GK in tuberculosis pathogenesis and immune activation, highlighting their potential as protein-level biomarkers for the assessment of treatment response." (PMID 40808944, 2025). "Collectively, these findings indicate that the host mounts a response to MTB infection by enhancing BH4 synthesis, underscoring the pivotal role of the GCH1 gene in the pathogenesis of tuberculosis." (PMID 40808944, 2025). "Future studies will aim to enlarge the sample pool to encompass tuberculosis (TB) patients and healthy controls from a broader array of geographic regions and ethnic backgrounds, thereby enabling a more comprehensive validation of the involvement of ASPHD2, GK, and GCH1 in the pathogenesis of TB." (PMID 40808944, 2025).
tyrosine hydroxylase deficiency (1 paper, 2018). Tyrosine hydroxylase (TH) deficiency is an autosomal recessive disorder characterized by a spectrum of phenotypic features, based on severity and response to levodopa. "One patient had tyrosine hydroxylase deficiency and other cases had GCH1 mutation." (PMID 29484265, 2018).
α-synucleinopathy (1 paper, 2020). "Since proteomic, human genetic and network analysis all highlighted Gch1 as a strong candidate for further investigation in α-synucleinopathy we proceeded to functional testing." (PMID 33311497, 2020). "One or more of these mechanisms may account for the enhancement of brain bioenergetic dysfunction by Gch1 knockdown we observe in our Drosophila α-synucleinopathy model." (PMID 33311497, 2020). "Thus, although the GWAS signal implicating GCH1 does not indicate the cell type responsible for the disease-modifying effect, our functional data are consistent with a critical role for GCH1 in neurons in influencing α-synucleinopathy pathogenesis." (PMID 33311497, 2020).
cancer (38 papers, 2011 to 2026). A tumor composed of atypical neoplastic, often pleomorphic cells that invade other tissues. "Additional deletion of GCH1 in YAP/TAZ-deficient LLC cells not only sensitized these cells to ferroptosis but also prevented the propagation of ferroptosis resistance between cancer cells." (PMID 40619484, 2025). "Inhibition of GCH1 activity increases the susceptibility of drug-resistant cancer cells to ferroptosis." (PMID 36505465, 2022). "When performing GSEA for canonical pathways using the C2 gene set, we found that some lncRNAs, including lnc-BOD1-1:7, -1:8, and -1:9, as well as lnc-GCH1-2:1, -2:2, and -2:3 were associated with many immune- and cancer-associated pathways." (PMID 31810243, 2019). "In humans, the GCH1 PP haplotype has been associated with reduced risk of chronic pain after discectomy as well as a slow progression of pain in cancer patients." (PMID 23421753, 2013). "The study subjects were homozygous carriers of the GCH1 variant, and it was noted that the time between cancer diagnosis and the need for opioid therapy initiation was longer than in heterogenous individuals." (PMID 21808743, 2011). "GCH1 expression levels in cancer cells stratified susceptibility to ferroptosis." (PMID 40143150, 2025). "The expression of the GCH1 gene in cancer is linked to poor prognosis and increased cancer grade." (PMID 36908807, 2022). "Indeed, loss of GCH1, 6-pyruvoyl-tetrahydropterin synthase or sepiapterin reductase sensitize cancer cells to GPX4 inhibition and overexpression of GCH1 is sufficient to increase resistance to Gpx4 loss and inhibition and imidazole ketone erastin (IKE) treatment." (PMID 38908072, 2024). "Studies have found that GCH1 upregulation in certain cancer cells increases BH4 levels, thus enhancing resistance to ferroptosis." (PMID 41323780, 2025). "GTP cyclohydrolase 1 (GCH1)-BH4 is demonstrated highly expressed in cancer cells tolerant to ferroptosis." (PMID 39309434, 2024). "Clinical, demographic, psychological, cancer treatment-related variables, quantitative sensory testing, and patient genotype (COMT, OPRM1, GCH1, ESR1, and KCNJ6) were assessed as risk factors using multiple logistic regression." (PMID 37184910, 2023). "Our data demonstrate an increase in GCH1 induced by niraparib at both mRNA and protein levels in cancer cell lines, which was further validated using PDX-derived tissue sections." (PMID 36793373, 2023). "The results show that the combination of GCH1 inhibitor and erastin can synergistically inhibit the growth of cancer cells." (PMID 36309489, 2022). "In recent years, it has come to light that Sepiapetrin reductase (SPR) and GTP cyclohydrolase I (GCH1) play a crucial role in the metabolic processes of cancer cells." (PMID 36908807, 2022). "Spr and Gch1 have some pivotal roles in the metabolic processes of cancer cells; thus, we investigated these genes expression in the present study." (PMID 36908807, 2022). "Through the differential analysis of expression in pan-cancer, GCH1 was observed to be up-regulated in most tumor tissues." (PMID 35281840, 2022). "Inhibition of GCH1 activity results in the sensitivity of drug-resistant cancer cells to ferroptosis." (PMID 36505465, 2022). "More importantly, it was also implied that the level of GCH1 expression determined cancer cell resistance to ferroptosis and that GCH1/BH4 enriched reduced CoQ10, making further efforts to mitigate ferroptosis progression." (PMID 33996593, 2021). "Moreover, increased expression of GCH1 enhances the immunogenicity of cancer cells; herein, knockdown of GCH1 leads to the disruption of immune-related anticancer responses." (PMID 41583517, 2026).
cancer (continued). "Additionally, future studies using clinical samples are needed to validate the relationship between YAP/TAZ heterogeneity and GCH1 in human cancer." (PMID 40619484, 2025). "GCH1 overexpression selectively protects membrane phospholipids from peroxidation, and the level of GCH1 expression exhibited a substantial correlation with the sensitivity of cancer cells to ferroptosis." (PMID 40557156, 2025). "GCH1 overexpression and ferroptosis resistance then occur in cancer cells." (PMID 41323780, 2025). "This suggests that the GCH1/BH4 pathway can be a cancer treatment target." (PMID 41323780, 2025). "The first reports of BH4 as a ferroptosis suppressor indicate that cancer cell lines with high levels of GCH1 expression could be more dependent on BH4 for ferroptosis protection." (PMID 38908072, 2024). "Thus, GCH1 is not only a target for cancer therapy focusing on ferroptosis but also a potential strategy for new cancer therapies that utilize the immune response function of GCH1." (PMID 39723384, 2024). "Based on the finding that the GCH1 low-expression group in ESCC correlates with poor prognosis, we hypothesized that GCH1 contributes to cancer malignancy." (PMID 39723384, 2024). "Therefore, further studies are necessary to elucidate the role of GCH1 in other cancer types to gain a better understanding of its significance in cancer." (PMID 38903179, 2024). "The inhibition of GCH1 was proved to be an effective way to manage cancer pain." (PMID 36793373, 2023). "In addition, in cultured cells, overexpression or underexpression of GCH1 made cancer cells correspondingly resistant or sensitized to ferroptosis." (PMID 36309489, 2022). "GCH1 expression level determined ferroptosis sensitivity in cancer cells." (PMID 34447410, 2021). "Similar to FSP1, there is a clear correlation between GCH1 expression and the resistance of cancer cells to ferroptosis, indicating that the GCH1-BH4-phospholipid axis may be a potential target in tumor therapy." (PMID 34611144, 2021). "Hence, suggesting reduced GCH1 upregulation delays the need for opioid initiation in cancer treatment." (PMID 21808743, 2011). "However, research on the expression and biological functions of GCH1 in cancer is still limited." (PMID 36793373, 2023). "However, the administration of niraparib induced an almost double anticancer effect in siGCH1-transduced cells compared to the control, indicating that inhibition of GCH1 could potentiate PARP inhibitor therapy in cancer." (PMID 36793373, 2023). "In addition to CHOL, KICH, KIRC, KIRP, and LIHC, GCH1 expression is up-regulated in other cancers." (PMID 35281840, 2022). "The GTP cyclohydrolase 1 (GCH1) and its metabolic products, tetrahydrobiopterin (BH4) and dihydrobiopterin (BH2), have been reported to protect cancer cells from ferroptosis." (PMID 38368399, 2024). "The expression level of GCH1 determines the BH4 availability, which influence the redox balance in cancer cell." (PMID 36505465, 2022). "To comprehensively understand these four lncRNAs (LINC01224, CASC9, LINC00346, and TRPM2-AS) and seven target mRNAs (CCNF, PKMYT1, GCH1, TK1, PSAT1, ADAM33, and DDX11), we performed genome instability, immune, cancer stemness, and drug sensitivity analysis." (PMID 34368141, 2021). "Therefore, targeting GCH1, in addition to depleting GPX4 and FSP1, can effectively induce ferroptosis in cancer cells that are resistant to apoptosis." (PMID 39723384, 2024). "Coincidentally, two independent teams have discovered GTP cyclohydrolase-1 (GCH1)- tetrahydrobiopterin (BH4) pathway protects cancer cells from ferroptosis independent of GSH." (PMID 35999642, 2022). "A single-cell transcriptional analysis of four independent datasets indicated that GCH1 had a relatively high expression in monocytes/macrophages, B cells, CD4+ T cells, and CD8+ T cells, but low or no expression in malignant tumor cells." (PMID 36072600, 2022).